IL1B (interleukin 1 beta)
Diseases named in the same sentence as IL1B in open-access papers (continued):
Sharing a sentence is not in itself a finding about the gene and the disease.
periodontitis (continued). "THSG and resveratrol both inhibited the expression of proinflammatory cytokines such as IL-1β and TNF-α, which are involved in pathogenesis of periodontitis." (PMID 27504055, 2016). "Periodontitis is an inflammatory disease in which higher expression of TNF-α, IL-1β and LPS were found in the periodontal microenvironment in patients." (PMID 27216891, 2016). "The IL-1β and IL-6 levels increased, whereas the TNF-β levels decreased with the severity of periodontitis (4 mm pocket percentage)." (PMID 25884025, 2015). "In serum, significant concentrations of IL-6 and TNF-α were present during the evolution of periodontitis and reactional lesions, while IFN-γ and IL-1β were related with T1R, T2R, and CPD." (PMID 26339136, 2015). "A consensus report of the 7th European Workshop on Periodontology recently highlighted interleukin (IL)-1β, IL-6, tumor necrosis factor (TNF)-α, and RANKL as important players in the periodontitis network." (PMID 26734583, 2015). "Particularly, IL-1β, MIP-1α, and arginase are strong biomarkers that correlate with inflammatory parameters of periodontitis, such as the gingival index or BOP." (PMID 26389079, 2015). "Among cytokines, IL-1β and TNF-α are essential in the development and progression of periodontitis, as it has been shown that their antagonists inhibit the inflammatory response in experimental PD." (PMID 25587321, 2014). "A panel of 8 SNPs in VEGF, ACT, HMG-CR, INF-γ, IL-1β, IL-10, IL-6 and TNF-α genes in patients with periodontitis and controls (CTR) was studied and genotype distributions and allele frequencies were obtained." (PMID 24274085, 2013). "The aim of this study is to compare genotypes and soluble protein of pro and anti-inflammatory cytokines (IL-1α, IL-1β, IL-6, IFN-γ, IL-10, TNF-α and IL-4) in subjects with or free of chronic periodontitis." (PMID 23046796, 2012). "After ligature removal, the expression of IL-1β and TNF-α significantly decreased in the periodontitis group at week 1, 2, and 4 compared with baseline level (P < 0.05)." (PMID 23326020, 2012). "It showed that both the IL-1β/bFGF ratio and TNF-α/bFGF ratio were highest at baseline in periodontitis and periodontitis/stress group." (PMID 23326020, 2012). "The proinflammatory cytokine, interleukin (IL)-1β, is suggested to play a role in the regulation of local inflammatory responses in both CVD and periodontitis." (PMID 21362180, 2011). "We confirm that the model of periodontitis used here leads to a substantial increase in the levels of TNF-α and IL-1β in the gingivomucosal tissue." (PMID 21253492, 2010). "Out of the most studied genes in aggressive periodontitis [IL1-A and IL1-B (2q14), IL-4 (5q31.1), IL-10 (1q31-q32), FcγRIIa, FcγRIIb, and FcγRIIIb (1q23), and TNFA (6p21.3)], IL-4 and TNFA map in the intervals with suggestive association results." (PMID 20383335, 2010). "IL-1 receptor antagonist (IL-1RA) is an endogenous inhibitor that competes with IL-1α and IL-1β for receptor binding without activating downstream signalling; its elevation in periodontitis often reflects an inadequate compensatory response." (PMID 41583507, 2026). "Also, the mean levels of TNF-α and IL-1β in the saliva and GCF of patients with periodontitis were significantly higher than in patients with gingivitis." (PMID 40265034, 2025). "Accordingly, by amplifying IL‐1β expression, ECV may serve as a DAMP that promotes inflammation in periodontitis." (PMID 40346842, 2025). "While the classification features included WBC, serum IL-1β, Trig/HDL ratio, NE/LY ratio, and HDL, grading included HDL-C, LDL-C, NE/LY ratio, CHOL, and salivary IL-1β, which served no purpose staging classification and periodontitis grading." (PMID 40802302, 2025). "Similarly, reported that in saliva, the dual combinations of IL‐1β, IL‐6 and MMP‐8 have an excellent ability to detect periodontitis and a good capacity to detect non‐periodontitis, but a meta‐analysis of gingival crevicular fluid biomarkers was not possible." (PMID 39801446, 2025).
periodontitis (continued). "Early periodontitis can increase salivary and serum concentrations of NLRP3, an important inflammatory marker that governs the activation of IL-1β and its pro-inflammatory effects, which include the recruitment of neutrophils and other cells innate immune systems." (PMID 41440361, 2025). "In patients with periodontitis and hyperlipidemia, intensive periodontal treatment reduced the serum triglyceride and proinflammatory cytokine levels, that is, tumor necrosis factor-alpha (TNF-α), interleukin (IL)-1β (IL-1β), and IL-6." (PMID 40552326, 2025). "This study aims to comprehensively evaluate and compare the diagnostic performance of salivary biomarkers interleukin-1 beta (IL-1β) and matrix metalloproteinase-8 (MMP-8) in identifying periodontal disease across its various stages, including health, gingivitis, and periodontitis." (PMID 40283051, 2025). "Elevated levels of pro-inflammatory cytokines, such as IL-1β and IL-6, along with matrix metalloproteinases like MMP-8, contribute to the degradation of connective tissue and bone resorption, driving the clinical manifestations of periodontitis." (PMID 40283677, 2025). "Similarly, the mean level of IL-1β in the saliva and GCF of patients with periodontitis was higher than in the gingivitis group and healthy individuals." (PMID 40265034, 2025). "In this study, salivary IL-1β concentrations were found to be higher in the gingivitis group than in the periodontitis group, although not significantly." (PMID 39964474, 2025). "It has been reported that although salivary IL-1β levels in patients with periodontitis were significantly reduced after non-surgical periodontal therapy, they still remained significantly higher than in healthy controls." (PMID 40430061, 2025). "This synergistic interplay among IL-6, IL-1β, and TNF-α drives extracellular matrix degradation, osteoclastogenesis, and progressive alveolar bone resorption, thereby contributing to the irreversible tissue breakdown characteristic of advanced periodontitis." (PMID 41007333, 2025). "In chronic periodontitis, LPSs derived from P. gingivalis stimulate peripheral monocytes and macrophages to produce proinflammatory mediators such as TNF-α and IL-1β, which can compromise the integrity of the BBB and, upon penetrating the brain, exacerbate neuroinflammation." (PMID 39860036, 2025). "Yücel et al13 observed varying IL-1β concentrations in GCF between groups, with higher rates in the gingivitis group than in the chronic periodontitis group, different from our results, indicating higher levels in patients with periodontitis." (PMID 40265034, 2025). "In this review, the regulatory role of exosomal miR-223-3p in periodontitis was also highlighted, specifically its ability to suppress NLRP3 inflammasome-mediated pyroptosis and the release of pro-inflammatory cytokines such as IL-1β and IL-6 in macrophages." (PMID 41322905, 2025). "Immunofluorescence further demonstrated that macrophage polarization in vivo shifted in response to therapy: periodontitis lesions were dominated by M1 macrophages (high CD86 and IL‐1β, low CD206 and IL‐10), whereas HIPPE‐QU treatment skewed macrophages toward the M2 phenotype." (PMID 41020683, 2025). "Given the parallel between rheumatoid arthritis and periodontitis, it is remarkable that anakinra, as a potent inhibitor of the common denominator IL-1β, has not been studied in models for periodontitis." (PMID 40136507, 2025). "Furthermore, the use of LDN57444, a specific UCH‐L1 inhibitor, enhanced the osteogenesis of PDLSCs exposed to tumour necrosis factor alpha (TNF‐α) or IL‐1β, suggesting a destructive role of UCH‐L1 in periodontitis progression." (PMID 39626954, 2025). "Importantly, elevated levels of IL-1β and MMP-9 are correlated to periodontitis, with higher levels found in periodontitis compared to healthy individuals." (PMID 41303313, 2025).
periodontitis (continued). "Cytokines, such as interleukin-1β (IL-1β), tumor necrosis factor-alpha (TNF-α), and acute-phase proteins, including CRP, which are secreted during periodontitis, enhance systemic inflammation, which in turn aggravates endothelial dysfunction and plaque formation." (PMID 40418274, 2025). "In addition to IL-1β, levels of IL-2, IL-8, and IL-13 were significantly elevated in the GCF of periodontitis sites compared to healthy and gingivitis sites (p < 0.05)." (PMID 41303313, 2025). "In addition, in the LR, LRP2, and LRP5 groups, lower levels of TNF-α and IL-1β were observed in both tissue and serum samples, similar to the finding that TNF-α and IL-1β levels were correlated with the degree of periodontitis and decreased after SRP." (PMID 39941567, 2025). "Periodontitis is characterized by a persistent immune inflammatory response to bacterial biofilms, leading to systemic dissemination of cytokines such as tumor necrosis factor (TNF)-α, IL-1β, IL-6, and prostaglandins." (PMID 40941475, 2025). "Also, the mean levels of TNF-α and IL-1β in the saliva and GCF of patients with periodontitis were significantly higher than patients with gingivitis (P<0.05)." (PMID 40265034, 2025). "Additionally, the continuous presence of IL-17 induces various inflammatory mediators in endothelial cells, epithelial cells, and fibroblasts, such as IL-1β, TNF-α, and IL-6, which contribute to the activation of osteoclasts in periodontitis." (PMID 40248692, 2025). "One can conclude that IL-1β is more related to the BOP and PPD parameters, which could discriminate among periodontitis statuses." (PMID 39445112, 2024). "Physical training resulted in a reduced levels of IL-1β, IL-6, TNF-α C-reactive protein and LPO and an increase in the levels of IL-10 in rats with periodontitis (p<0.05); a reduction in the inflammatory infiltrate and decreased fiber degradation was identified in histological analysis." (PMID 38843156, 2024). "Additionally, we conducted immunohistochemical analysis to explore the protein translation of IL1β, SRGN, CXCR1, and PTAFR in patients with periodontitis." (PMID 38491529, 2024). "In this study, we aimed to (i) detect Td-dentilisin and MMP-8 immunoexpression levels in gingival tissue samples of patients with periodontitis compared with periodontally healthy gingivae to (ii) assess the MMP-8, MMP-2, MMP-7, TIMP-1, and IL-1β mRNA expressions in the diseased vs. healthy gingiva." (PMID 38786309, 2024). "Osteocalcin (OC), IL-1β, tumor necrosis factor-alpha (TNF-α), interleukin-6 (IL-6), OPG, and matrix metalloproteinase-9 (MMP-9) were significant in oral fluid or saliva, and they were from periodontitis, MRONJ, and osteoporosis." (PMID 39410587, 2024). "Additionally, periodontal tissue affected by periodontitis showed an increase in the M1 inflammatory factors TNF-α and IL-1β as well as the M2 inflammatory factor IL-10." (PMID 38347915, 2024). "Furthermore, previous studies have shown that PL effectively downregulates IL-1β expression in a mouse model of osteoarthritis, as well as inhibits TNF-α and IL-6 levels in a rat model of chronic periodontitis, which aligns with our observations." (PMID 38655086, 2024). "Additionally, even though IL-17, IL-1β and TNF were proven to be relevant in mouse models, it is important to question their relevance in the C5-periodontitis axis among humans." (PMID 39439802, 2024). "It is not surprising that salivary levels of IL-1β were increased in the periodontitis groups in this study, as previously reported." (PMID 39445112, 2024). "On the other hand, it is known that the MMP-8′s up-regulator’s IL-1β mRNA and activator MMP-7 mRNA and potential endogenous inhibitor TIMP-1 mRNA can be de novo transcriptionally up-regulated in the diseased periodontitis gingivae." (PMID 38786309, 2024).
periodontitis (continued). "Our in vitro data align with this, showing IFN-γ pathway activation (IRF8, STAT1, IL-1β) during macrophage polarization under P. gingivalis infection, suggesting a positive link between RANKL and IFN-γ in regulating osteoclast differentiation in periodontitis." (PMID 39595193, 2024). "IL1A, IL1B, CXCL1, and CXCL3 displayed some correlation with highly infected cells —mostly suprabasal cells, likely explaining the differentiation effects predicted for these cells in periodontitis." (PMID 38876998, 2024). "Notably, studies have revealed elevated levels of Prostaglandin E2 (PGE2), TNF-α, and IL-1β and functional impairment of polymorphonuclear leukocytes (PMNs) in T1DM individuals, presenting with gingivitis or periodontitis." (PMID 39301048, 2024). "This strip simultaneously detects three periodontitis biomarkers: MMP-8, IL-1β, and TNF-α." (PMID 39554809, 2024). "The serum levels of TNF-α and IL-1β, key proinflammatory cytokines, were highest in the group of rats induced with periodontitis without treatment, confirming the presence of active inflammation." (PMID 39539670, 2024). "A central role seems to be played by two cytokines in periodontitis: TNF-α and IL-1β." (PMID 38792574, 2024). "Several inflammatory factors are relevant to the periodontitis, such as TNF-α, IL-1β, and IL-641." (PMID 38698209, 2024). "Catechin’s suppressive effect on IL-1β and TNF-α production may provide a beneficial approach for modulating periodontitis." (PMID 37509571, 2023). "Moreover, some promising biomarkers of periodontitis were suggested, such as matrix metalloproteinase-8 (MMP-8), matrix metalloproteinase-9 (MMP-9), interleukin 1 beta (IL1β), and interleukin 6 (IL6)." (PMID 37535199, 2023). "Some studies have found that smoking periodontitis patients showed elevated levels of proinflammatory cytokines, such as IL-1β and TNF-α, compared with nonsmoking periodontitis patients." (PMID 36726081, 2023). "Indeed, higher levels of pro-inflammatory cytokines (IL-1β, IL-6, TNF) were found in blood and gingival fluid in obese subjects with periodontitis compared to normo-weighted subjects with periodontitis." (PMID 37894804, 2023). "Ligature-induced periodontitis (LIPD) induced elevated gingival senescence biomarker expression, particularly in old mice, with a ~4-fold increase in SA-b gal, ~12-fold increase in p16 INK4A, ~4-fold increase in TNFa, and ~7-fold increase in IL-1β." (PMID 36818565, 2023). "While in the established periodontitis mouse model, NAC‐S2 administration significantly decreases CEJ to ABC distance and suppresses the expression levels of pro‐inflammatory cytokines including TNF, IL‐6, and IL‐1β." (PMID 37647428, 2023). "Furthermore, higher IL-1β levels in GCF and similar levels of TNF-α have been demonstrated in patients with OSA and periodontitis." (PMID 36967976, 2023). "EXO-NET EVs display increased IL-6, IL-8, and IL-1β in periodontitis individuals compared to those without, with significantly reduced IL-10 expression." (PMID 39697803, 2023). "The expression of IL1B in tumor tissue is more closely related to the prognosis of HNSCC, while serum IL1B is also altered by non-tumor inflammatory diseases, such as periodontitis, arthritis, and enteritis, among others." (PMID 36969073, 2023). "Similarly, in our study, we find that NAC‐S2 treatment significantly suppresses the mRNA expression levels of TNF, IL6, and IL‐1β in gingival tissues of periodontitis mice, indicating the protecting role of NAC‐S2 in periodontitis." (PMID 37647428, 2023). "Unlike the other 3 genes, it is specifically the alternate SNPs, (A) allele of IL1B-511 and (C) allele of IL10-1082, that promote strong GCF exudation, efficient bacterial removal from the crevice and mild or no periodontitis." (PMID 37762554, 2023).
periodontitis (continued). "The increased salivary levels of macrophage inflammatory protein (MIP)-1α and prostaglandin E2 (PGE2) but not interleukin (IL)-1β, IL-6, and IL-8 are reported in gingivitis, an initial stage of periodontitis." (PMID 38068492, 2023). "IL-6, nitric oxide, IL-1B, TNF-α and osteoprotegerin are among the most present biomarkers in patients with periodontitis, and may be used in the future as a monitoring of periodontal disease." (PMID 37026605, 2023). "In the present meta-analysis, we found that smoking periodontitis patients have significantly higher GCF IL-1β values than nonsmoking patients after periodontal therapy." (PMID 36726081, 2023). "This is because nicotine induces harmful effects on systemic health, reducing the activity of the immune system and increasing the production of pro-inflammatory cytokine interleukins (IL)-1β and tumor necrosis factor-alpha (TNF-α), thereby increasing the severity of periodontitis." (PMID 37109642, 2023). "Increased levels of IL-1β and TNF-α in the GCF occur in periodontitis." (PMID 37623272, 2023). "The results showed that smoking patients with periodontitis had significantly higher IL-1β levels in the GCF after periodontal therapy than nonsmoking periodontitis patients." (PMID 36726081, 2023). "We previously reported that sIL-6R was detected at higher levels in the GCF of periodontitis sites than in healthy sites and that these molecules induce MMP-1 expression in the secondary response to IL-6 produced by IL-1β and indirectly activate intracellular signaling pathways in HGFs." (PMID 36834667, 2023). "However, periodontitis also triggers systemic inflammation, indicated by an increased level of C-reactive protein (CRP), TNFα, IL-1β, and IL-6 in the serum of patients." (PMID 35874771, 2022). "Unlike the finding in the current systematic review, another study demonstrated that IL-1β gene expression was lower in smokers with chronic periodontitis than in non-smokers with chronic periodontitis (p = 0.003)." (PMID 36361498, 2022). "TNF-α, IL-1β, and IL-6 were increased in serum, and VCAM-1 and ICAM-1 were increased in the atherosclerotic plaques of ApoE KO periodontitis mice, accompanied by increased Oil-Red O-stained plaque areas of the aorta after the subgingival injection of LPS for 10 weeks." (PMID 36232471, 2022). "Significant higher salivary levels of IL-6 and IL-1β were found in the periodontitis group when compared to the nonperiodontitis group (p=0.005; p < 0.001, respectively)." (PMID 35368315, 2022). "IFN-γ, IL-1β, and TNF-α are elevated in chronic periodontitis compared to healthy controls." (PMID 35189698, 2022). "Similarly, in experimental periodontitis, there is an increase in the circulating levels of CRP, IL-1β, IL-6, and of neutrophils." (PMID 35052857, 2022). "In both studies, saliva samples were collected during the 3rd trimester and authors found a higher prevalence of periodontitis as well as significantly higher levels of TNF-α, IL-1β, total antioxidant capacity (s-TAC) and CRP, particularly when GDM was diagnosed." (PMID 36432584, 2022). "In inflammatory bone diseases such as periodontitis, the nucleotide-binding oligomerization domain, leucine-rich repeat, and pyrin domain-containing 3 (NLRP3) inflammasome accelerates bone resorption by promoting proinflammatory cytokine IL-1β production." (PMID 35682777, 2022). "Additionally, using a periodontitis mouse model, higher amounts of NLRP3 and IL-1β were visible in the inflamed gingiva." (PMID 35563469, 2022). "Interleukin-1β (IL-1β), IL-6, tumor necrosis factor alpha (TNF-α), and receptor activator of nuclear factor kappa B ligand (RANKL) are significant markers of the pathogenesis of periodontitis." (PMID 36050950, 2022). "Processing of proinflammatory cytokine IL-1β is regulated by nucleotide-binding oligomerization domain-like receptor protein 3 (NLRP3) inflammasome complex, and NLRP3 expression is upregulated in the gingival tissue of patients with periodontitis." (PMID 36319994, 2022).